IL33 (interleukin 33)
Diseases named in the same sentence as IL33 in open-access papers (continued):
Sharing a sentence is not in itself a finding about the gene and the disease.
asthma (continued). "Several neutralizing antibodies against IL-33 are currently in early phases of clinical development as therapeutic approaches for asthma, COPD (chronic obstructive pulmonary disease), atopic dermatitis, or chronic rhinosinusitis with nasal polyps." (PMID 33615121, 2021). "In a murine asthma model, glycoproteins from Sphingomonas induced type 2 inflammation via natural killer T cells in an IL-4-, IL-13-, and IL-33-dependent manner." (PMID 33831071, 2021). "IL-33 belongs to the IL-1 cytokine family and induces allergic responses, such as asthma, allergic rhinitis, and atopic dermatitis." (PMID 34576749, 2021). "IL-33 is one of the most representative members of the alarmin family and it is involved in asthma pathogenesis due to its key role in the activation of type 2 immune response." (PMID 34608100, 2021). "Another study found an association between a Mediterranean diet pattern and lower levels of IL-4 and IL-17, but higher levels of IL-33, in both males and females with asthma." (PMID 33503979, 2021). "In a mouse model of persistent house dust mite (HDM)-induced asthma characterized by mixed granulocytic influx in the lungs the anti-IL-33 treatment was shown to prevent airway remodeling." (PMID 34084159, 2021). "IL-33 is highly expressed in airway mucosa or nasal polyps isolated from patients with asthma, and its expression level is well correlated with disease severity." (PMID 34093589, 2021). "Should lipid peroxidation be involved in IL33-driven allergy or asthma in response to phospholipases or other allergens (e.g. proteases) will require additional study." (PMID 34516571, 2021). "In a mouse model of asthma, manipulation of airway miR-206 expression altered IL-25, IL-33, and Tslp expression; ILC2 expansion; and type 2 airway inflammation." (PMID 33945508, 2021). "TSLP, IL-25 and IL-33 are involved in the pathophysiology of allergic diseases, including asthma and atopic dermatitis, as they activate the Th2-dependent immune response." (PMID 34301307, 2021). "In particular, several GWAS for asthma have reported the involvement of the IL-33–IL-1RL1 receptor pathway, with CDHR3 and ORMDL3 being the loci associated with induced eosinophilia and Th2 inflammatory or viral responses." (PMID 34946955, 2021). "Gorska and colleagues reported that the levels of IL-33 in serum, induced sputum, exhaled breath condensate, and bronchial mucosa were similar between asthma and COPD." (PMID 33722239, 2021). "While anti-IL-33 antibodies have now largely been abandoned in asthma, trials are still ongoing in other allergic diseases, including peanut allergy and atopic dermatitis." (PMID 33917396, 2021). "In this study, imiquimod decreased gene expression of cytokines of special interest in asthma pathogenesis such as IL-33 and IL-1β." (PMID 34950134, 2021). "In asthma, IL-33 is defined as an “activating cytokine” that induces proliferation and type 2 cytokine production by ILC2s via the NF-κB signaling pathway." (PMID 35126350, 2021). "Severe and corticosteroid-resistant endotypes of asthma are often characterized by high neutrophil counts in sputum, increased levels of IL-33, the formation of neutrophilic traps and activation of the inflammasome." (PMID 34484177, 2021). "For example, while astrocyte-derived IL-33 is critical for healthy neuronal development, stromal cell–derived IL-33 in the lung provides a pathologic niche, which exacerbates asthma, allergic responses, and helminth infections." (PMID 34699382, 2021). "Increased expression of IL-33 according to asthma severity in human has been reported in several studies." (PMID 33722239, 2021). "This is corroborated by various clinical studies, both in children and adults, which correlate the levels of IL-33 with asthma disease severity and steroid-unresponsiveness." (PMID 35387021, 2021). "In a mouse model of asthma using an evaluation of bronchial contraction ex vivo, IL‐33 stimulation was correlated with airway hyperresponsiveness." (PMID 34617355, 2021).
asthma (continued). "IL-33 is a well-known factor in asthma, one of the several lung diseases where IL-33 plays a relevant role." (PMID 34441830, 2021). "Our data in an otherwise unselected population of children with severe asthma showed that IL-33 appeared to be an important mediator." (PMID 32349347, 2020). "IL-33 is a member of the IL-1 superfamily and has been forwarded as a multifactorial alarmin cytokine with critical roles in T2 immunity and asthma pathophysiology." (PMID 33255348, 2020). "In animal experiments, injection of sST2 or ST2 blocking antibody can alleviate asthma mediated by IL-33 and block the proinflammatory effect of IL-33 on rheumatoid arthritis." (PMID 33344656, 2020). "Interleukin (IL)-33 plays important roles in pulmonary immune responses and lung diseases including asthma and chronic obstructive pulmonary disease (COPD)." (PMID 32903501, 2020). "Thymic stromal lymphopoietin (TSLP), IL-33, and IL-25 are three epithelial-derived cytokines with critical roles in asthma pathogenesis as they are potent activators of DCs and ILC2s, which act upstream in the T2 immune response cascade." (PMID 33255348, 2020). "Mouse experiments suggest that IL-33 is involved in development of airway hyperresponsiveness (AHR), a hallmark feature of asthma." (PMID 32903501, 2020). "Multiple genome-wide association studies have identified both the IL-33 and ST2 genes as asthma susceptible loci in humans." (PMID 32903501, 2020). "Clinical phase 2 trials with monoclonal antibodies targeting either IL-33 or ST2 are currently ongoing and will evaluate the potential of IL-33 as a therapeutic target in asthma." (PMID 33255348, 2020). "Actions of IL-33 on MCs are related to exacerbation of antigen-driven airway inflammation occurring in asthma, and the blockage of IL-33 has been proposed as a therapeutic strategy for allergic reactions." (PMID 33158024, 2020). "Taken together, both ex vivo and in vivo experiments strongly suggest that PD-1 deficiency is associated with a metabolic shift toward glycolysis, thus enhancing ILC2 activation and proliferative potential in IL-33-induced asthma." (PMID 32778730, 2020). "The aim of the study was to evaluate the impact of interactions between DCs and nasal epithelial cells co-cultured with macrophages on the expression of TSLP, IL-33, and IL-17A in asthma, COPD, and controls." (PMID 32842623, 2020). "In this study, we demonstrate that ILC2 expression of adhesion molecules LFA-1 and ICAM-1 play crucial roles in the development of IL-33-induced asthma symptoms, albeit at different levels." (PMID 33193309, 2020). "TSLP, IL-33, and IL-17A expression in moDCs are differently regulated by epithelium in asthma, COPD, and healthy subjects." (PMID 32842623, 2020). "In agreement with a previous study that showed that IL-33 was increased in asthma, HDM extract increased IL-33 expression and secretion in alveolar epithelial cells." (PMID 32793232, 2020). "For instance, Regeneron Pharmaceuticals, in collaboration with Sanofi, entered Phase 2 clinical trials for asthma, chronic obstructive pulmonary disease and atopic dermatitis with an anti-IL-33 antibody (REGN3500)." (PMID 32754154, 2020). "IL-33 can promote type 2 responses, and as such, IL-33 is an important mediator of asthma and other allergic diseases." (PMID 32397226, 2020). "Another study showed that asthma severity in children correlated with IL-33 expression in submucosal regions––a region in which many hematopoietic-derived cells reside––rather than in the epithelium or smooth muscle." (PMID 31940364, 2020). "Particularly, IL‐33 and ST2 were two major susceptibility loci shown to be associated with human asthma." (PMID 32566227, 2020). "The function of the IL-33/ST2 axis has been investigated in asthma, suggesting an important role in allergic disease." (PMID 32719716, 2020).
asthma (continued). "This same group later showed a key role for IL-33 as a driver of asthma exacerbations: antibody blockade of the IL-33 receptor reduced AHR as effectively as systemic corticosteroids." (PMID 33101299, 2020). "IL-33 has been found to be involved in the occurrence of many diseases, such as atherosclerosis and obesity, and plays a pro-inflammatory role in asthma and antigen-induced arthritis." (PMID 33308251, 2020). "Transgenic overexpression of soluble IL-33 in mice results in lethal inflammation and autoimmunity, and elevated levels of IL-33 are found in mouse models of allergic airway inflammation and in severe asthma in human patients." (PMID 33376451, 2020). "Children with severe asthma with fungal sensitization (SAFS) have greater IgE titers and an association with elevated IL-33." (PMID 33324573, 2020). "Among them, IL-33 and its receptor ST2 were identified with asthma, which suggests the importance of the IL-33 pathway." (PMID 32397396, 2020). "Overwhelming evidence supports a central role for the three epithelial-derived cytokines, TSLP, IL-33, and IL-25, in asthma." (PMID 33255348, 2020). "This is clinically relevant, as polymorphisms in both IL-33 and ST2 closely associate with asthma in human patients." (PMID 31940364, 2020). "In summary, IL-33 deficiency alleviated disease severity and decreased CD146 expression and EMT in asthma." (PMID 32793232, 2020). "Work by the Sperling group supported a similar role for DC-derived IL-33 in an immune complex–mediated model of Th2 priming and asthma." (PMID 31940364, 2020). "Serum IL-33 and the soluble form of ST2 are closely associated with asthma disease progression and exacerbation." (PMID 32793232, 2020). "Recently, asthma mouse models induced by proteases, such as papain or cytokines, including IL-25- and IL-33, have also been established." (PMID 32397396, 2020). "Yet, emerging evidence suggests the involvement of the T2-promoting cytokines IL-25, IL-33, and TSLP in the response to respiratory viruses and associated exacerbations in asthma." (PMID 33255348, 2020). "In humans, increased levels of IL-33 have been observed in epithelial cells and sera of patients with exercise-induced asthma." (PMID 32486265, 2020). "In Rag2−/−Il2rg−/− mice (lacking T cells, B cells, and ILCs), the levels of eosinophilic inflammation and the secretion of mucus decreased significantly, highlighting the importance of the IL-33/ILC2s axis in the development of asthma." (PMID 33597946, 2020). "This suggests a crucial role of IL-33 in modulating immune cells functioning in several pathologies such as asthma and lung diseases." (PMID 31973226, 2020). "Previous studies found that miR-146a administration in vivo alleviated the symptoms of ovalbumin (OVA)-induced asthma in mice through the IL-33 pathway." (PMID 32600285, 2020). "In fact, Clinicaltrials.gov has listed anti‐IL‐33 clinical trials in patients with asthma, food allergy, chronic rhinosinusitis and chronic obstructive airway disease (accessed 19 February 2020)." (PMID 32566227, 2020). "In the present study we have identified SERPINA3I as a novel regulator of IL-33 processing in a murine asthma model." (PMID 33072128, 2020). "Recently, IL-33 has been considered as an important factor of the immune system involved in allergic inflammation and chronic diseases such as asthma, atopic dermatitis, and allergic rhinitis." (PMID 32971846, 2020). "We showed that our compound is effective, safe and effectively blocks the important for asthma development inflammatory processes like lung eosinophils accumulation and up-regulation of IL-33 expression." (PMID 32702053, 2020). "IL-33 has emerged as a mediator that orchestrates the pathogenesis of airway eosinophil-related allergic disease, including asthma and CRS." (PMID 33218117, 2020). "Bronchial hyperreactivity is typical in the course of asthma and IL-33 has been identified as inducing this process." (PMID 31057533, 2019).
asthma (continued). "IL-33 also promotes asthma-related IL-4 and IL-13 production from basophils via MyD88-signaling pathway." (PMID 30886621, 2019). "IL-33 highly contributes to the development of chronic inflammatory diseases such as asthma and COPD." (PMID 31057533, 2019). "Previously, IL-33 was suggested to be closely associated with asthmatic development and exacerbation in animal model study, as IL-33 levels are increased when the severity of asthma is increased in mouse." (PMID 31197082, 2019). "IL-33 is beneficial in the setting of wound healing but exacerbates allergic inflammation in some models of asthma." (PMID 30682073, 2019). "Currently, more studies are necessary to elucidate the functional roles of IL-33 and involved mechanisms during immune responses including asthma." (PMID 31823765, 2019). "IL-33, an alarmin that is highly expressed in airway epithelial cells, has been shown to be overexpressed in lungs of patients with pulmonary fibrosis, asthma, and COPD and has been shown to be a main driver of ILC2 expansion." (PMID 31354734, 2019). "As we found the link between Glrx and IL-33 signaling in macrophages, we extended the findings to examine expression of Glrx and IL-33 in a relevant mouse model of asthma." (PMID 30682073, 2019). "Increased levels of IL-33 in lung epithelial cells and blood serum has been observed in asthma patients." (PMID 31057533, 2019). "IL-33 can promote the pathogenesis of Th2-related diseases like asthma, atopic dermatitis and anaphylaxis." (PMID 30846811, 2019). "The cells are recruited through the activity of IL-33, and are useful in the immunity against pathogens, type 2 inflammation, tissue homeostasis, and repair, and pivotal in conditions like asthma and atopic dermatitis." (PMID 30769901, 2019). "Among respiratory disorders, the contribution of IL-33 to the development of asthma, in particular, has been most identified." (PMID 31057533, 2019). "Increased level of IL-33 in lung epithelial cells and blood serum has been observed in asthma patients." (PMID 31057533, 2019). "Feedback circuit involving both IL-33 and ILCs responsible for bronchial hyperactivity and persistence of asthma has been suggested based on the animal model of the disease." (PMID 31057533, 2019). "They found evidence of association of pLoF variants located at well-known IL33 and GSDMB asthma loci with lower risk of both asthma and allergic rhinitis." (PMID 30805318, 2019). "AMG 282 and ANB020 has been developed in clinical trials on asthma, and it is a drug that targets soluble IL-33." (PMID 31284537, 2019). "There is a correlation between IL-33 positive cells in the submucosa and reticular basement membrane thickness in children with severe therapy resistant asthma." (PMID 30941335, 2019). "Three known asthma loci replicated in CAAPA, after a Bonferroni correction for 810 association tests: chromosomes 9p24 (RANBP6, IL33), 15q22 (RORA,NARG2,VPS13C), and 17q12–q21." (PMID 30787307, 2019). "Another clinical trial concerning anti-IL-33 antibody in asthma patients is in phase 1 and compares it to the placebo Dupilumab and fluticasone propionate (ClinicalTrials.gov: NCT03112577)." (PMID 31057533, 2019). "During asthma, pulmonary fibrotic changes are mediated by interleukin-33 (IL-33)-enhanced amphiregulin production by memory T helper 2 cells." (PMID 31382483, 2019). "In several genome wide association (GWA) studies it has been established that both genes encoding IL-33 and its receptor IL1RL1 are susceptibility loci for asthma." (PMID 31057533, 2019). "The release of the major stimulators of ILC2s, TSLP, IL-25, and IL-33, as a result of epithelial cell injury in both asthma and COPD, provide evidence of ILC2s in airway remodeling." (PMID 31354734, 2019). "The critical role of IL-33 was confirmed by GWAS studies showing that IL-33 and ST2 genes were significantly associated with asthma." (PMID 31355170, 2019).
asthma (continued). "Both anti-TSLP and anti–IL-33 therapies were clinically proven to reduce asthma exacerbations and allergic dermatitis symptoms, respectively, and are moving forward in clinical development." (PMID 31184997, 2019). "IL-33 (ILC2 activator, besides TSLP and IL-25)) was also associated to airway remodeling in steroid resistant asthma." (PMID 31395084, 2019). "Previous studies have shown that IL-33-responding ILC2s occur in influenza virus-induced hyper-reactivity and present as asthma-like symptoms." (PMID 31509992, 2019). "A small synthetic molecule mimetics of α-helical domain of IRAK2 called compound 7004, which can inhibit the IL-33–induced NF-kB activity, disrupt myddosome formation, and attenuate the pro-inflammatory effects in an asthma-like animal model." (PMID 30886621, 2019). "Among these genes, only the expression of IL-33 was detected to be increased when all asthma patient samples were included to analysis." (PMID 31798831, 2019). "On the basis of the concept that rhinovirus is one of the most common asthma exacerbation triggers, they built up a human experimental model in order to detect IL-33 levels during the rhinovirus infection in asthmatic and healthy airways." (PMID 31766607, 2019). "Due to its inflammatory and Th2-skewing potential, IL-33 is critical in the induction and maintenance of allergic disorders, such as asthma, atopic dermatitis, and allergic rhinitis." (PMID 30979016, 2019). "Several clinical trials targeting either IL-33 or its receptor in asthma and COPD are ongoing at the moment." (PMID 31057533, 2019). "The relationship between IL-33 and asthma has been demonstrated using an IL-33-overexpressing transgenic mouse, which showed asthmatic airway inflammation with an influx of inflammatory cells and increased expression levels of Th2 cytokines." (PMID 31197082, 2019). "Therapeutic inhibition of IL-33 signaling is gaining interest with anti-ST2 antibodies being trialed for asthma." (PMID 31227713, 2019). "IL-33 induces allergic diseases, such as asthma, through the activation of various immune cells that express an IL-33 receptor, ST2, including ST2+ memory (CD62LlowCD44hi) CD4+ T cells." (PMID 30972065, 2019). "Anti-IL-33 biologics are currently in clinical trials for asthma and other atopic conditions and will be expected to significantly impact eosinophil function in allergic disorders." (PMID 31490928, 2019). "Immunization of mice to a single dose of ovalbumin (OVA) together with IL-33 induces long-lasting memory TH2 cells that leads to severe asthma-like pathology in the lungs." (PMID 30949175, 2019). "IL-33 is a pro-inflammatory cytokine which mediates several immune functions; its involvement in a wide range of diseases, such as atopic dermatitis, asthma, and rheumatoid arthritis, is now emerging." (PMID 30846811, 2019). "IL-33 and its receptor ST2 are associated with a variety of inflammatory diseases, such as asthma, rheumatoid arthritis, atopic dermatitis, inflammatory bowel disease, and cardiovascular disease including atherosclerosis." (PMID 29373608, 2018). "IL-33 plays an important role in driving mast cell responses and promoting type-2 allergic inflammation, particularly with respect to asthma, via MyD88-integrated crosstalk amongst the IL-33 receptor (ST2), TLR4 and FcεRI." (PMID 29540770, 2018). "Several studies demonstrating a role of IL-33/ST2 in diseases associated with a Th2 response (i.e., asthma) remarked that ST2L is a cell surface marker in addition to its function as an effector molecule in the regulation of Th2 cell pathway." (PMID 29713240, 2018). "In asthma mice model with exposure to pneumonia virus, anti-IL-33 decreases Th2 inflammation by suppressing rhinovirus replication and increasing IFN-λ levels." (PMID 29987222, 2018). "In those with asthma, IL-33 pre-exposure and RV stimulation augmented ST2 mRNA expression and elevated the frequency of ST2+ILC, whereas sST2 production was low." (PMID 30174671, 2018).